CCNB1 (cyclin B1)
Diseases named in the same sentence as CCNB1 in open-access papers (continued):
Sharing a sentence is not in itself a finding about the gene and the disease.
glioma (continued). "Increasingly numerous results have demonstrated overexpression of CDC2/Cyclin B1 in various tumors however there is still no report of CDC2/Cyclin B1 expression in clinical samples from patients with gliomas." (PMID 18230152, 2008). "In glioma tissues of GBM, mesenchymal subtype cells have the high expression of mesenchymal subtype signature genes, including chitinase 3 like 1 (CHI3L1), collagen type V alpha 1 chain (COL5A1), fibronectin 1 (FN1), cyclin B1 (CCNB1), and maternal embryonic leucine zipper kinase (MELK)." (PMID 35158782, 2022). "In basal conditions, we show that the inhibition of EPOR affects the cell cycle of glioma cells with a G2/M arrest accompanied with an increase in the cyclin B1 expression, an indicator of G2/M arrest but not that of cyclin D1 expression, a critical mediator of G1 to S phase progression." (PMID 25544764, 2015). "Silencing EPOR on glioma cells exposed to ionising radiation (X-rays) or chemotherapy (TMZ) enhances senescence and induces mitotic cell death, an effect that may be through an increase in cyclin B1 expression." (PMID 25544764, 2015). "Moreover, to uncover the potential molecular mechanisms by which TAGLN2 promote glioma development, we detect the expression change of FoxM1, an oncogenic transcriptional factor that regulates some key mediators of cell cycle progression, including CDK2, cyclin B1, cyclin D1, p21 and p27." (PMID 29110682, 2017).
colon carcinoma (46 papers, 2010 to 2025). "These are also known to inhibit the production of cyclin‐dependent kinase 2 and cyclin B1, two proteins that are related to an enhanced risk of colon cancer." (PMID 40078339, 2025). "Curcumin inhibited the gene expression of Cdc25c, CDK1, and cyclin B1 and promoted the gene expression of Wee1 in colon cancer cells, causing cell cycle arrest at the G2/M phase." (PMID 33233354, 2020). "To study the underlying molecular mechanisms of USP22/CCNB1 crosstalk in colon cancer development, we first confirmed their interaction." (PMID 27030811, 2015). "Cyclin B1 is one of the key regulators of the G2/M transition, and gene amplification or overexpression of cyclin B1 is associated with cell growth and tumorigenesis in colon cancer." (PMID 24885395, 2014). "Furthermore, pseudoguaianolide (a 5/7 bicyclic compound) SLs of 6-O-angeloylplenolin, coronopilin, pulchelloid A and hymenoratin caused G2/M-phase arrest by activating cyclin B1-Cdk1/p-Cdk1 in multiple myeloma, leukemia and colon cancer cells, respectively." (PMID 35056723, 2022). "STIL knockout showed different blockade phases in different tumor types, and reduced the proliferation of cervical and colon cancer cells by inhibiting Cyclin B1/CDK1, which, in turn, induced cell cycle arrest in the G2/M phase." (PMID 36497260, 2022). "The in vitro results further confirmed that AE and QR inhibited the proliferation of HCT116 colon cancer cells and significantly reduced CCNB1 expression." (PMID 35479514, 2022). "In this study, we identified six cyclin genes (CCNA2, CCNB1, CCND1, CCNE1, CCNF, and CCNJL) that are potential diagnostic biomarkers of colon cancer." (PMID 33996604, 2021). "Although LOC441461-knockdown-induced suppression of CCNB1 was observed in all colon cancer cells, the suppression of CCND1 and CDK4 was observed in SW620, DLD-1, and LS174T cells but not LoVo cells." (PMID 33126743, 2020). "In the present study, we demonstrated that MUM256 EA reduced the proliferation of colon cancer cells by arresting cells at G1 and G2 phases through the modulation of cell-cycle regulatory proteins including p21, cyclin B1, CDK2, CDK4 and cdc25A phosphatase." (PMID 31698795, 2019). "Induction of G2/M arrest by TAX and NOC with increases in phosphorylated Cdc25C and cyclin B1 protein were observed in human colon cancer cells." (PMID 31906029, 2019). "Of these compounds, the G2/M arrest of cordycepin, which regulated cyclin D1, cyclin B1 and p21 protein, has been investigated in melanoma, bladder and colon cancer cells." (PMID 29522490, 2018). "Collectively, these results suggested that α-hederin reduced viability and arrested cell cycle associated with downregulation of cyclin B1 and CDK2 in colon cancer cells." (PMID 30363706, 2018). "MiR-93 was once reported to slow cell proliferation and migration through direct degradation of p21 and CCNB1 in colon cancer, thus arresting the cell cycle in G2 stage." (PMID 29245924, 2017). "On the one hand, USP22 is a CCNB1 deubiquitinase that promotes cell cycle progression and colon cancer cell growth." (PMID 27030811, 2015). "Our discovery here, that both USP22 and CCNB1 proteins are elevated and positively associated in human colon cancers, indicates that USP22-mediated CCNB1 stabilization is one possible molecular mechanism underlying its proto-oncogenicity." (PMID 27030811, 2015). "First, both USP22 and CCNB1 protein expression are elevated with a strong positive correlation in human colon cancer tissues." (PMID 27030811, 2015). "We found that GSC treatment resulted in downregulation of Cdc25c and cyclin B1 expression in HT-29 colon cancer cells." (PMID 22474493, 2012).
colon carcinoma (continued). "Previously, inappropriate increases in nuclear Cyclin B1 have been found in mitotic catastrophe in colorectal adenocarcinomas, nasopharyngeal carcinoma, and colon cancer." (PMID 22428049, 2012). "While its role in MM pathogenesis is not well understood, cyclin B1 high expression predicts a favorable outcome in patients with follicular lymphoma, and a cyclin B1-accumulating agent induces mitotic arrest of HCT-116 colon tumor cell line." (PMID 21755010, 2011). "For example, cyclin B1 is a predictor of the effect of Chk1 inhibitors in numerous types of cancer, including colon cancer, which might be applied to the stratification of colon cancer." (PMID 35884370, 2022). "Gene sets of mTORC1 signaling, KRAS signaling, and oxidative phosphorylation were also significantly enriched, which may unravel the process of cyclin genes (especially CCNB1) in colon cancer." (PMID 33996604, 2021). "High levels of cyclin B1 and D1 were observed in oxaliplatin-resistant colon cancer cells." (PMID 33578797, 2021). "Cell cycle is a continuous system of biological processes, and several studies have elucidated that the lower level of CDK1 and CCNB1 in colon tumor cells slowed down the G2/M phase of the cell cycle, which owned to the retardation of cell cycle in the S phase." (PMID 33628185, 2020). "Furthermore, we find a positive correlation between USP22 and CCNB1 expression in human colon cancers." (PMID 27030811, 2015). "Upregulation of either CCNB1 or USP22 has been found in human colon cancers." (PMID 27030811, 2015). "Because it is an essential cell cycle regulator, malfunctioning of CCNB1 might be proto-oncogenic, as its expression is often upregulated in various types of human cancers, including colon cancer, cervical cancer and renal cancer." (PMID 27030811, 2015). "As both USP22 and CCNB1 are upregulated and positively correlated in colon cancer, targeting either of them might be a good approach to cancer therapy." (PMID 27030811, 2015). "Next, we questioned whether USP22 is involved in the elevated CCNB1 protein expression in human colon cancers." (PMID 27030811, 2015). "Additionally, because phosphorylation of cyclin B1 is important for cyclin-B1/cdc2 kinase activation, we suggest that treatment of MB-653 triggers a dose-dependent accumulation of G2/M phase colon cancer cells through the dysfunction of the cyclin B1/CDC2 complex." (PMID 39858466, 2025). "Therefore, USP22 is an interacting partner of CCNB1 in human colon cancer cells." (PMID 27030811, 2015). "Thus, our study identified USP22 as an interacting protein of CCNB1 in human colon cancer cells." (PMID 27030811, 2015). "A total of 27 anticolon cancer targets of THCQF were selected, among which four genes (CCNB1, CCNA2, IL1A, and MMP3) were shown to effectively predict patient outcomes in a prognostic colon cancer model." (PMID 35479514, 2022). "By downregulating the cell cycle checkpoint proteins cyclin B1 and CHK2, colon cancer Caco-2 cells showed an anti-proliferative effect." (PMID 35455970, 2022). "Given the potential of the four important cyclin genes (CCNA2, CCNB1, CCNE1, and CCNF), we further investigated the genes co-expressed with them in colon cancer via WGCNA." (PMID 33996604, 2021). "Among the four datasets of colon cancer from The Cancer Genome Atlas and the Gene Expression Omnibus, six cyclin genes (CCNA2, CCNB1, CCND1, CCNE1, CCNF, and CCNJL) were differentially expressed between normal and tumor tissues." (PMID 33996604, 2021).
colon carcinoma (continued). "It is reported that the interaction between CDK1/cyclin B1 complex and ZNFX1 antisense RNA 1 (ZFAS1) leads to cell cycle progression and cell apoptosis suppression in the progression of colon cancer." (PMID 30186855, 2018). "In fact, immunoblotting analysis confirmed dramatically higher protein expression levels of both CCNB1 and USP22 in colon cancer tissues (in 7 of 10 patients) compared with those in adjacent normal controls." (PMID 27030811, 2015). "Elevated levels of both CCNB1 and USP22 indicate more aggressive cancer and a poor prognosis and both of these proteins were upregulated in colon cancer patients." (PMID 27030811, 2015). "Herein, we identify USP22 as a CCNB1 interactor and discover that both USP22 and CCNB1 are dramatically elevated with a strong positive correlation in colon cancer tissues." (PMID 27030811, 2015). "We found that suppression of CNDP2 blocked cell cycle progression and decreased the expression of cyclin E, cyclin B1 and EGFR in colon cancer cells." (PMID 24885395, 2014). "Combined with these findings, we speculated that MMP1 might accelerate the cell cycle transition of colon cancer cells by regulating cdc25a/CDK4-cyclin D1 and p21/cdc2-cyclin B1 complexes through alteration in the expression of c-Myc and ETV4." (PMID 34753916, 2021). "It was reported that CCNB1 and CCND1 were elevated in colon tumor tissues." (PMID 33996604, 2021). "Overall, patients with lower expression of the four genes (CCNA2, CCNB1, CCNE1, and CCNF) had worse survival outcomes, which implies that these members of the cyclin family might be ideal prognostic biomarkers for colon cancer." (PMID 33996604, 2021). "The interaction between endogenous USP22 and CCNB1 in human colon cancer cells was also detected, as anti-CCNB1-specific antibody but not normal mouse immunoglobulin G immunoprecipitated USP22 protein." (PMID 27030811, 2015). "Moreover, they also found that the expression of CCNB1 was positively correlated with tumor-killing immune cells, such as CD8+ T cells, which may prolong the survival time of patients with colon cancer." (PMID 34858418, 2021). "BEND5 overexpression in DLD-1 colon cancer cells and BEND5 knockdown in COLO 320 DM colon cancer cells indicated that BEND5 could significantly change their expression levels, suggesting that BEND5 may directly or indirectly regulate CCNB1, PCNA and BCL2." (PMID 29371920, 2017). "Our results showed that EVO, EVO-5, and EVO-8, but not EVO-4, significantly induced G2/M arrest with increased cyclin B1/cad25c protein expressions and caspase-3/PARP protein cleavage in both colon carcinoma cell lines." (PMID 24959718, 2014).
pancreatic cancer (46 papers, 2007 to 2025). "Silencing of cyclin B1 in pancreatic cancer cells was associated the inhibition of cellular proliferation and an increase in the G0/G1 cell population." (PMID 39139643, 2024). "According to previous reports, silencing Nuf2 by RNA interference can inhibit the proliferation of pancreatic cancer cells and cause cell cycle arrest in the G0/G1 phase by inhibiting Cyclin B1, CDC2, and Cdc25A." (PMID 35393397, 2022). "In this study, we demonstrated that AR-42 inhibited growth of pancreatic cancer cells in vitro and in vivo, and caused cell cycle G2/M arrest by regulating expression levels of cyclin B1, cyclin B2, CDK1, and p21." (PMID 28829799, 2017). "Several studies have detected a decrease in cyclin B1 levels and an increase in cell cycle progression inhibitors p21 and p27 upon alisertib-induced cell cycle arrest in breast, ovarian and pancreatic cancer cells." (PMID 40723174, 2025). "Herein, we report that R. coriaria extract downregulated the levels of both cyclin E and cyclin B1 in pancreatic cancer cells." (PMID 39139643, 2024). "In contrast to our findings, a study of 40 pancreatic cancer tissue samples reported a significant difference in CCNB1 expression between cancerous and normal pancreatic tissues, establishing a link between high CCNB1 expression and increased tumor grade." (PMID 39795587, 2024). "Trichostatin A (TSA) and SK-7041 caused G2/M cell cycle arrest by upregulating p21 and downregulating cyclin B1, the anti-apoptotic protein Mcl-1, and Bcl-XL in pancreatic cancer cell lines." (PMID 37628767, 2023). "CCNB1 has been extensively studied in many solid tumours, such as lung, hepatic, and pancreatic cancers." (PMID 36418517, 2023). "CCNB1 has been observed to expedite tumor cell division, cell proliferation, and tumor growth in colorectal and pancreatic cancers." (PMID 37007961, 2023). "For example, the silencing of CCNB1 in pancreatic cancer cells promotes cell senescence, inhibiting cell proliferation and promoting cell apoptosis." (PMID 35456460, 2022). "To date, C646 has been documented to transcriptionally repress tumor formation in breast and pancreatic cancer growth by suppressing cyclin B1 and CDK1." (PMID 35205642, 2022). "ASPM, CCNB1, CDK1, MELK, OAS3, PPTG1 and TOP2A were thought to be significantly associated with shorter overall survival in pancreatic cancer patients." (PMID 36167975, 2022). "Subsequently, we examined the mRNA expression of CCNB1 in pancreatic cancer cell lines and the protein level via HPA database." (PMID 36167975, 2022). "The expression of CCNA2, CCNB1, CDC6 and GAPDH have all been implicated in various cancers, including lung, ovarian and pancreatic cancer." (PMID 32899298, 2020). "Morusin also targets the STAT3 pathway and its downstream targets, including survivin, cyclin B1, to exert antitumor activity in prostate and pancreatic cancers." (PMID 32906784, 2020). "IC50 of silibinin in AsPC-1 pancreatic cancer cells was determined to be 224.20 and 87.25 μM after 48 and 72 hr, respectively cyclin E2, cyclin A and cyclin B1 were decreased." (PMID 32489562, 2020).
pancreatic cancer (continued). "Of the approximately 1000 genes represented on the chip, 40 were down-regulated by 50% or more after ICG-001 treatment, including CCNB1 and ALDH1A, genes associated with cell cycle regulation and pancreatic cancer stem/progenitor cells, respectively." (PMID 29596326, 2018). "DATS, a garlic-derived organosulfur compound, showed growth inhibitory effects on pancreatic cancer cells (Capan-2) through elevated levels of cyclin B1 and p21 and reduced levels of cyclin D1." (PMID 25401123, 2014). "In both in vivo (50, 100, 200 μM/L) and in vitro (4 mg/kg, for 30 days) studies, crocetin exhibited inhibitory effects on cell proliferation in pancreatic cancer cells by significantly modifying the expression of Cdc-2, Cdc-25C, Cyclin-B1, and epidermal growth factor receptor." (PMID 38419885, 2024). "Similarly, overexpression of cyclin B1, a cell cycle regulator involved in the regulation of G2/M phase, has been consistently correlated with increased pancreatic cancer incidence, much so that it is now considered a prognostic factor for the same." (PMID 39139643, 2024). "Moreover, previous studies have reported that curcumin induces G2/M arrest and cyclin B1 change in pancreatic cancer cells." (PMID 37239055, 2023). "Furthermore, inmmunohistochemical results and patient clinical data were obtained from the HPA database, which showed significantly higher in situ expression of CCNB1 in pancreatic cancer tissues as compared with normal pancreatic tissues." (PMID 36167975, 2022). "CCNB1 expression is relatively higher in pancreatic cancer tissues." (PMID 35664322, 2022). "In this study, Spiclomazine arrests the cell cycle by inhibiting the expression levels of Cyclin B1 and CDK1 involved in G2 phase in these pancreatic cancer cell lines." (PMID 29467941, 2018). "Next, we investigated the levels of pro-apoptotic Bim, E-cadherin, cyclin B1, and CDK4, which are known to play a critical role in regulating the proliferation, differentiation and apoptosis of pancreatic tumors." (PMID 22509328, 2012). "To further investigate the molecular mechanism of Spiclomazine-induced cell cycle arrest, we evaluated the effect of Spiclomazine on the expression levels of Cyclin B1 and CDK1 involved in G2 phase in these pancreatic cancer cell lines for 24 hours using WB assay." (PMID 29467941, 2018). "Depletion of RLIP76 by antisense significantly increased the levels of the pro-differentiation marker E-cadherin and pro-apoptotic protein Bim while decreasing the levels of anti-apoptotic protein Bcl2, cyclin B1 and CDK4 in both BxPC3 and Panc-1 pancreatic cancer cells." (PMID 22509328, 2012). "To conclude, our present observations state that curcumin treatment potentially inhibits the proliferation of BxPC-3 human pancreatic cancer cells by DNA damage-mediated G2/M cell cycle arrest by the activation of ATM/Chk1/Cdc25C and inhibition of cyclin B1/Cdk1 expression." (PMID 19401701, 2009). "However, studies have not identified a significant association between CCNB1 protein expression and TNM staging in pancreatic cancer." (PMID 39795587, 2024). "In the pancreatic cancer tissues, we confirmed that protein levels of LARP7, CDK1, and CCNB1 increased notably in tumor tissues compared with non-tumor tissues." (PMID 36434634, 2022).